IL13RA2 (interleukin 13 receptor subunit alpha 2)
Diseases named in the same sentence as IL13RA2 in open-access papers (continued):
Sharing a sentence is not in itself a finding about the gene and the disease.
glioma (continued). "The results indicated that the modification of Pep-1 enhanced nanoparticle accumulation in the glioma section through IL-13Rα2 mediated endocytosis than unmodified NP which depended on limited EPR effects to get into tumor site." (PMID 26567528, 2015). "IL-13Rα2 is reported to be overexpressed on human tumors including glioma cell lines and with a high affinity for IL-13, which makes IL-13Rα2 an attractive target." (PMID 28344260, 2015). "We demonstrate that this fiber modification successfully redirects the viral tropism specifically to IL13Rα2-expressing glioma cells in vitro and in vivo." (PMID 26656559, 2015). "In orthotopic xenograft glioma-bearing animal models, the IL13Rα2-targeting CARs showed increased survival of treated animals when compared to untransduced T cells." (PMID 25247196, 2014). "IL13Rα2+ glioma targets were accurately targeted and eliminated by the CAR expressing T cells with abundant secretion of cytokines IL2 and IFNγ." (PMID 25247196, 2014). "When cultured in vitro together with glioma cells, they also lysed only IL13Rα2-expressing U251 glioma cells." (PMID 25247196, 2014). "These experiments were prompted by efforts to use cytokine-stimulation paradigms to increase IL13Rα2 expression on glioma cells and thereby increase the efficacy of IL13Rα2 targeted therapies for brain tumors." (PMID 24787244, 2014). "IL13Rα2 is expressed in approximately 58% of adult and 83% of the pediatric brain tumors as well as on glioma-initiating cells." (PMID 25247196, 2014). "We investigated the possibility of up-regulating cell surface IL13Rα2 levels on glioma utilizing cytokine stimulation regimens previously reported to induce IL13Rα2 on other cell types, including the monocytic cell line THP-1." (PMID 24787244, 2014). "For example, when evaluating cancer stem cells, our group found that IL13Rα2 is expressed by approximately 50% of glioma stem cell lines when using the AF146 antibody." (PMID 24787244, 2014). "Increased expression of IL13Rα2 has been reported to promote tumor progression in glioma and other tumor models." (PMID 25247196, 2014). "IL13Rα2 expression is a prognostic marker for glioma malignancy grade and for poor patient survival." (PMID 25247196, 2014). "T cells and expressing CARs for the glioma-specific antigens including IL-13Rα2, HER2, EGFRvIII, and EphA2 show potent antiglioma activity in preclinical animal studies." (PMID 25009822, 2014). "Our group has developed a platform to target high-grade gliomas based on IL13Rα2 expression by genetically modifying T cells to express an IL13Rα2-specific chimeric antigen receptor (CAR), IL13-zetakine." (PMID 24204956, 2013). "These engineered IL13-zetakine+ T cells exhibit potent MHC-independent, IL13Rα2-specific cytolytic activity against both stem-like and differentiated glioma cells, and induce regression of established glioma xenografts in vivo." (PMID 24204956, 2013). "Our findings now suggest that IL13Rα2 targeting will be skewed towards (but not limited to) the mesenchymal glioma subtype." (PMID 24204956, 2013). "In this study, we utilized multiple, large, publicly available datasets to examine IL13Rα2 expression on molecularly-characterized glioma subtypes." (PMID 24204956, 2013). "We find that within GBM, IL13Rα2 is over-expressed in approximately 58% of gliomas, and displays a distinct bimodal expression pattern." (PMID 24204956, 2013). "Our data also indicate that inter-patient heterogeneity of IL13Rα2 expression should be viewed in the context of molecular subtypes of high-grade gliomas." (PMID 24204956, 2013). "Immunohistochemical analyses of paraffin-embedded specimens demonstrated a diffuse membranous, partially cytoplasmic staining pattern in glioma cells for both IL-13Rα2 and EphA2 (respectively)." (PMID 18093336, 2007). "Antigens previously studied in CAR-T for high-grade gliomas include IL-13Rα2, EGFRvIII, and GD2." (PMID 40507329, 2025).
glioma (continued). "After a case of durable response to IL-13Rα2- targeting CAR-T in relapsed multifocal GBM was reported in 2009, a Phase 1 clinical trial was performed to evaluate safety and tolerability of a CAR-T product against IL-13Rα2 in recurrent high grade glioma, the majority of which was GBM." (PMID 40507329, 2025). "Recent studies indicate that IL-13Rα2 and EGFRvIII expression is significantly heterogeneous in glioma tissues, suggesting that strategies targeting both antigens simultaneously could achieve broader tumor coverage." (PMID 40092990, 2025). "Similarly, IL-13 muteins have been engineered into CARs for selective targeting of IL13Rα2-expressing gliomas, while natural receptor ectodomains such as NKp30 or NKp44 have been incorporated to leverage endogenous NK recognition mechanisms." (PMID 40941014, 2025). "Furthermore, recombinant immunotoxins composed of IL-13 ligand fused to Pseudomonas exotoxin have demonstrated the ability to selectively kill IL13Rα2-expressing glioma cells." (PMID 40918539, 2025). "Our next step of the research is to generate a murine counter part of CAR‐T cells with murine scFv‐IL‐13Rα2 as a transgene and test its quality attributes in vitro and in vivo in syngeneic mouse models using murine IL‐13Rα2 positive glioma cell lines such as GL121 and CTA2." (PMID 38685487, 2024). "The development of glioma vaccines aims to target tumor-specific antigens similar to those recognized by Chimeric Antigen Receptor T (CAR-T) cells, such as EGFR variant III (EGFRvIII) and Interleukin-13 Receptor Alpha 2 (IL-13Rα2)." (PMID 38534769, 2024). "Here, we integrated IL13RA2 into a construct encoding for PDGFB and used the RCAS/Tva system to develop a novel immunocompetent GEMM that both recapitulates diffuse midline gliomas and expresses the human glioma-associated antigen IL13RA2." (PMID 39711568, 2024). "Nevertheless, whether the association between IL-13Rα2 and FUS has clinical significance in human gliomas remains unclear." (PMID 37158824, 2023). "Importantly, both glioma stem-like cells and differentiated tumor cells express IL13Rα2, thus maximizing the circumference of IL13Rα2-targeted CAR T cell therapy." (PMID 36721153, 2023). "Combining cytokine transgene expression with viral oncolysis may amplify antitumor immune responses; #8 Interleukin-13 Receptor Alpha 2: The IL13Rα2 cluster suggests this glioma antigen is a promising target for cytokine-mediated immunotherapy." (PMID 38259287, 2023). "Furthermore, our in vitro data highlight the ability of BiKE to activate NK cells, mediate the killing of IL13Rα2-positive tumors, and increase the survival of IL13Rα2-positive glioma-bearing animals." (PMID 37443750, 2023). "For example, in a Phase 1 study of an EGFRvIII-specific CAR in GBM, a single dose of the CAR-T cells led to downregulation of the EGFR/EGFRvIII receptor, whereas IL13Ra2-specific CAR-T cells co-expressing IL-15 were potent against glioma but led to the rise of tumors with IL13Ra2 downregulation." (PMID 37420216, 2023). "Interestingly, SHN3 expression correlated with PTP1B and IL13Rα2 expression according to the Chinese Glioma Genome Atlas (CGGA) dataset." (PMID 37963919, 2023). "The affinity of IL-13 to IL-13RA2 was found to be stronger than that to IL-13RA1, which inhibits the IL-13RA1/IL-4R signaling pathway, suggesting IL-13RA2 as a powerful target for anti-glioma therapy." (PMID 36466873, 2022). "Anti-glioma antigen immune responses to IL-13Rα2 were observed in 10 of 13 evaluable patients." (PMID 35464460, 2022). "Furthermore, IL13Rα2 is considered as oncogene due to its selective and high expression in glioma cells along with inhibition of apoptosis subsequently." (PMID 35612318, 2022). "IL-13Rα2 peptide-pulsed DCs induce T cell responses in recurrent glioma patients." (PMID 35464460, 2022).
glioma (continued). "In addition, clinical, pre-clinical and in vitro studies have shown that IL13Rα2 is a potential target for killing of glioma cells and its targeting by Car-T cells is under clinical trial investigation." (PMID 35612318, 2022). "In patients with worse prognosis, the expression of these antigens was found more severe and could be possibly explained by certain hypothesis such as, glioma cells adopt overexpression of IL13Rα2 that protect it from immunosuppression." (PMID 35612318, 2022). "Jing Han and his colleagues showed that high IL-13Rα1 with or without IL-13Rα2 expression was associated with poor prognosis in patients with high-grade gliomas." (PMID 33553434, 2021). "Although the level of IL13Rα2 expression according to glioma grade has been investigated using only a small number of samples, researchers report increased IL13Rα2 expression in proportion to higher glioma grade." (PMID 34819930, 2021). "Similarly, it has been reported that the high expression of IL-13Rα2 is observed in 100% of pheochromocytoma, 66% of colorectal cancer, 62% of glioma, 50% of gastric cancer, and 7.5% of melanoma." (PMID 34201539, 2021). "An IL-13Rα2 antibody could bind to glioma cells, inhibit tumor growth, and improve the survival time in a glioma xenograft mouse model." (PMID 33450900, 2021). "The preliminary results of this study on a single patient reported glioma regression, but development of therapy resistance associated to the emergence of (IL-13Rα2) negative cells." (PMID 34168976, 2021). "Additionally, a limited number of CSC markers are currently available but their biological function needs to be fully characterized, such as CSPG4 in multiple cancer types, EGFRvIII and IL13Rα2 in gliomas, and EpCAM in prostate cancer." (PMID 33806296, 2021). "A CAR specific for both HER2 and MUC1 for breast cancer showed that dual targeting can lead to the delivery of complementary signals that enhance T-cell proliferation, and dual-target CARs specific for HER2 and IL13Rα2 mitigate antigen escape in a xenograft glioma model." (PMID 34831068, 2021). "However, in glioma, IL13Rα2 binds to IL-13 with higher affinity, allowing for sequestration of IL-13 away from IL13Rα1." (PMID 33176788, 2020). "In an orthotopic mouse model, they injected glioma cells that expressed both IL-13Ra2 and EGFRvIII." (PMID 32325898, 2020). "Furthermore, when IL-13Rα2 expression was compared between lower-grade glioma and high grade GBM, both IL-13Rα1 and IL-13Rα2 gene expression levels were significantly lower in lower-grade glioma compared with GBM." (PMID 29168083, 2018). "Thus, genetic modification of IL13Rα2-CAR T cells with sIL15 or mbIL15 presents a promising strategy to enhance their anti-glioma activity." (PMID 30400835, 2018). "The significance of AP-1 signaling though IL-13Rα2 in glioma samples is not clearly understood." (PMID 30572904, 2018). "Therefore, additional studies are needed to further delineate a role of IL-13Rα2 and AP-1 signal transduction pathway in glioma invasion and infiltration." (PMID 30572904, 2018). "Expression of IL-13Rα2 mRNA in glioma cell lines was determined by RT-qPCR." (PMID 30572904, 2018). "Similarly, IL-13Rα2 as an immunogen is the basis of a DIPG/high grade glioma vaccine trial [NCT01130077]." (PMID 29621254, 2018). "In conclusion, since IL-13Rα2 is overexpressed in a variety of human primary tumors including astrocytoma and glioma as well as metastatic tumors, we predict that IL-13Rα2 targeted agents such as IL-13PE will not only target primary tumors but also metastatic tumors." (PMID 30572904, 2018). "Therefore, we examined the effect of AG1478 inhibition on ERK1/2 activation in glioma cells co-expressing IL-13Rα2 and EGFRvIII." (PMID 29203859, 2017).
glioma (continued). "In an attempt to delineate the functional relationship between IL-13Rα2 and EGFRvIII in human gliomas, isogenic human glioma cell lines that expressed either IL-13Rα2, EGFRvIII, both or null were generated to recapitulate the heterogeneous nature of the human GBM tumors." (PMID 29203859, 2017). "Human glioma Gli36 cells were chosen to constitutively express IL-13Rα2 alone, EGFRvIII or both receptors as confirmed by immunoblotting analysis and denoted as Gli36.IL-13Rα2, Gli36.EGFRvIII and Gli36.IL-13Rα2/EGFRvIII, respectively." (PMID 29203859, 2017). "In addition, studies in animal models of glioma and pancreatic ductal adenocarcinoma have shown that IL-13Rα2 chain plays a critical biologic role in IL-13 cytotoxin-mediated therapy." (PMID 27351230, 2016). "The use of IL13 ligand itself is one way to direct therapy to the glioma-specific IL13Rα2." (PMID 26656559, 2015). "Thus, providing a treatment option that specifically targets IL13Rα2-expressing stem-like and differentiated glioma cells would be of benefit to the patients with some of the most aggressive and hardest to treat cancers." (PMID 26656559, 2015). "It was reported that Pep-1 (CGEMGWVRC) peptide could facilitate polymer nanoparticles targeting to glioma via IL-13Rα2 endocytosis." (PMID 26567528, 2015). "Furthermore, we show that the scFv47 can be successfully incorporated into an adenoviral vector and that the Ad5FFscFv47-CMV-GFP virus also exclusively infects IL13Rα2-expressing glioma cells in vitro and in vivo." (PMID 26656559, 2015). "Moreover, the scFv47 successfully redirects adenovirus to IL13Rα2 expressing glioma cells both in vitro and in vivo." (PMID 26656559, 2015). "The fluorescence of Pep-NP group was much stronger than that of NP group in the glioma section, indicating that Pep-1 peptide could facilitate the enrichment of nanoparticles in the glioma via IL-13Rα2 mediated endocytosis." (PMID 26567528, 2015). "However, the glioma-initiating cells derived from IL13Rα2+ tumors express IL13αR2 at levels similar to differentiated cells and were similarly sensitive to in vitro IL13 zetakine therapy." (PMID 25247196, 2014). "The glioma-specific antigens used in recent preclinical or clinical studies showing potent antiglioma effect include IL-13Rα2, human epidermal growth factor receptor 2 (HER2), epidermal growth factor receptor variant III (EGFRvIII), and erythropoietin-producing hepatocellular carcinoma A2 (EphA2)." (PMID 25009822, 2014). "In one in vitro study, an antibody specific to interleukin-13 receptor alpha 2 (IL-13Rα2) (a receptor up-regulated in glioma cells) was attached to the surface of nanoparticles and demonstrated tumor specificity and toxicity in U373 and U87 glioma cell lines." (PMID 23594406, 2013). "By several measures, IL13Rα2 expression in patient samples and low-passage primary glioma lines most consistently correlates with the expression of signature genes defining mesenchymal subclass tumors and negatively correlates with proneural signature genes as defined by two studies." (PMID 24204956, 2013). "A truncated form of this toxin conjugated to mutated interleukin IL-13 (mhIL-13-PE, marketed under the name Cintredekin Besudotox) specifically binds and kills glioma cells while sparing normal neural cells that lack the glioma-specific receptor for the interleukin (IL13Rα2)." (PMID 24202446, 2013). "Like MAGE-A3, IL-13Rα2 is a cancer testes antigen that is over-expressed in gliomas." (PMID 23186108, 2012). "Notably, IL13Rα2 is not expressed in healthy brain tissue and is associated with glioma migration and invasion, making it an especially attractive antigen to target GBM cells." (PMID 37443750, 2023). "In addition, TanCAR-redirected T cells targeting IL-13Rα2 or EphA2 in a xenograft mouse model, after subcutaneous injection of U87 glioma cells, were able to elicit greater tumor regression than single CAR-T cells with the potential for reduction of antigen escape and off-target cytotoxicity." (PMID 37443804, 2023).
glioma (continued). "Therefore, the expression pattern of IL-13Rα2 in glioma remains to be elucidated." (PMID 37158824, 2023). "In addition to glioma, IL13Rα2 is expressed in a variety of malignancies that could be treated by systemic administration of IL13-CAR T cell therapy." (PMID 35939683, 2022). "The expression of IL13Rα2 in gliomas could also be used to assess prognosis." (PMID 36261831, 2022). "Toxins have been evaluated in several anti-glioma studies targeting IL13Rα2, the urokinase-type plasminogen activator (uPA) receptor, growth factor receptors and transferrin receptors, due to their differential expression status in glioma cells when compared to normal brain cells." (PMID 33790740, 2021). "Although the functional significance of IL13RA2 expression is not fully understood, it is considered an inhibitory or decoy receptor in GBM that contributes to tumor growth and several studies have found that its overexpression is associated with higher glioma grades and poor patient prognosis." (PMID 34447744, 2021). "Finally, since IL-13Rα2 and AP-1 pathway is involved in cancer invasion and metastasis, blocking this pathway may inhibit invasion, infiltration and metastasis of CNS cancers." (PMID 30572904, 2018). "The B-D13 antibody has also been used to evaluate constitutive IL13Rα2 expression on a variety of cell types, including a new model cell line for oral cavity squamous cell carincoma, tumor initiating cells in adult human gliomas, and IL13Rα2 expression in human pediatric brain tumors." (PMID 24787244, 2014). "The potential for targeting IL13Rα2-expressing GBMs has been demonstrated by early clinical experience at City of Hope in two phase I clinical trials with intracranial administration of first-generation IL13 zetakine T cell clones in patients with high-grade gliomas." (PMID 25247196, 2014). "Additionally, novel IL-13RA2-targeted adenoviral and herpes constructs have been developed and could potentially be used as gene therapy vectors for the treatment of gliomas." (PMID 24147065, 2013). "In addition, survival analyses indicate that IL13Rα2 over-expression is associated with poor patient prognosis, a single gene correlation ranking IL13Rα2 in the top ~1% of total gene expression probes with regard to survival association with WHO IV gliomas." (PMID 24204956, 2013). "A mathematical model analyzing the expression hierarchy of three validated glioma antigens (HER2, IL13Rα2, and EphA2) predicted an increased likelihood of tumor elimination when any two of these three antigens are targeted." (PMID 40092990, 2025). "We next sought to investigate the cytotoxic potential of our mRNA-based single-targeting (HER2 CAR, IL13Rα2 CAR, or EphA2 CAR) and multi-targeting (CARPool#2 and MVCAR#2) CAR T cells against patient-derived glioma cells." (PMID 40896578, 2025). "An ongoing phase I trial is evaluating IL13Rα2-specific CAR T cells in solid tumors, including NETs, building on prior applications in melanoma and glioma." (PMID 41300999, 2025). "Among these, IL13Rα2 is considered the most suitable target for GBM, as it is overexpressed in approximately 50-80% of gliomas, while remaining undetectable in normal brain tissue." (PMID 40092990, 2025). "These tumor cell lines can be engineered to express tumor-specific antigens such as EGFRvIII, IL13Rα2 and GD2 to create CAR T-cell glioma models." (PMID 39273050, 2024). "Adaptive T cells therapies which include IL13Rα2-CAR-T cells, IL13Rα2 is known to promote tumor regression in glioma and few other tumor models." (PMID 38523646, 2024). "One PDX, namely BT74, was used to accurately recapitulate glioma heterogeneity and the physiological expression of two GBM antigens, namely EGFRv3 and IL13Rα2, in pre-clinical studies of CAR T-cell approaches." (PMID 39273050, 2024). "Elevated IL13Ra2 levels were notably observed in pontine gliomas, diffuse intrinsic pontine gliomas (DIPGs), H3F3A-mutant gliomas, and WHO IV gliomas." (PMID 38201655, 2024).